WNK1 (WNK lysine deficient protein kinase 1)
Diseases named in the same sentence as WNK1 in open-access papers (continued):
Sharing a sentence is not in itself a finding about the gene and the disease.
breast carcinoma (13 papers, 2017 to 2025). "Taken together, we demonstrate that by destabilizing ERBB2, we controlled and downregulated YES1 and WNK1 that are well-known causes of drug resistance in ERBB2+ trastuzumab drug-resistant breast cancer and in osimertinib-resistant EGFR T790M lung cancer, respectively." (PMID 37359373, 2023). "Another significant finding of this study is that VNLG-152R caused dose-dependent depletion of WNK1 which is implicated in cell migration, invasion, and metastasis in multiple cancer types including glioblastoma, prostate cancer, non-small cell lung cancer, and breast cancer." (PMID 37766871, 2023). "The same finding was made in ERBB2+ trastuzumab-resistant breast cancer, in that the control of ERBB2 leads to loss of kinases such as WNK1 and YES1 implicated in this cancer mechanism of resistance." (PMID 37359373, 2023). "WNK1 is involved in many cancers including liver cancer, breast cancer, glioblastoma, giant cell tumors, retinoblastoma, clear-cell renal-cell carcinoma, and lung adenocarcinoma." (PMID 36292952, 2022). "MiR-93 suppresses WNK1 to reduce breast cancer malignancy, while it enhances the expression of STAT3." (PMID 32612456, 2020). "Our data support this role for WNK1, as knockdown of WNK1 resulted in reduced migration of breast cancer cells in response to BMCM." (PMID 28498874, 2017). "WNK1 promotes tumor migration and invasion in breast cancer." (PMID 40510161, 2025). "In breast cancer, WNK1 regulates AXL, a tyrosine kinase related to metastasis, independent of OSR1." (PMID 36292952, 2022). "Paralleling findings in endothelial cells, WNK1 has been implicated in migration with epithelial-mesenchymal (EMT) features through knockdown studies in multiple cancer types, and also as a contributor to stem-like properties in metastatic breast cancers." (PMID 35813203, 2022). "Also, work from our lab has shown that WNK1 inhibition in five different breast cancer cell lines MDA-MB-231, BT-549, BT-20, HCC1569, and HCC1419 significantly reduced the migratory capacity concomitantly with the reduction in N-cadherin protein expression." (PMID 35813203, 2022). "Both WNK-1 and Akt phosphosignaling are enriched in breast cancer." (PMID 33738261, 2021). "WNK1 is a proposed oncogenic kinase found to be mutated in colorectal adenocarcinoma and breast cancer, whose role in cancer is not fully elucidated." (PMID 29914080, 2018). "Its role in this pathway could cause WNK1 to be indirectly phosphorylated by the interaction of bone-derived OPN with αvβ3 on breast cancer cells, and thus could contribute to breast cancer migration, invasiveness and cell growth downstream of OPN." (PMID 28498874, 2017). "While experimental studies have demonstrated a role for the PI3K pathway in bone metastasis of breast cancer, to the best of our knowledge neither WNK1 or PRAS40 have previously been specifically implicated in bone metastasis." (PMID 28498874, 2017). "Utilizing transposon-mediated insertional mutagenesis for identifying candidate BC driver genes, WNK1 was identified as one of a handful of driver genes in high-risk invasive breast cancer." (PMID 35813203, 2022). "We demonstrate that bone-derived OPN promotes the migration and stem-like properties of breast cancer cells via the cell surface receptor CD44 and RGD-dependent cell surface integrins, resulting in activation of WNK-1 and PRAS40." (PMID 28498874, 2017). "We observed that bone-derived OPN specifically promoted the phosphorylation of WNK-1 and PRAS40, and that these pathways are important for mediating the migration of breast cancer cells in response to BMCM." (PMID 28498874, 2017). "This study also shows that bone-derived OPN activates a downstream signaling response in breast cancer cells involving the phosphorylation of WNK-1 and PRAS40, and that these pathways contribute to enhanced migration of breast cancer cells in the context of the soluble bone microenvironment." (PMID 28498874, 2017).
breast carcinoma (continued). "We observed that knockdown of WNK1 resulted in a significant reduction of breast cancer cell migration in response to BMCM relative to a non-specific siRNA control (P≤0.05)." (PMID 28498874, 2017).
lung carcinoma (11 papers, 2016 to 2024). "WNK1 mutations were previously reported to be associated with breast, ovarian, colorectal, and lung cancers." (PMID 30020984, 2018). "They concluded that low expression of STK10 and WNK1 proteins in the EVs of lung cancer patients correlated with a good prognosis of lung cancer compared to the healthy population." (PMID 38561776, 2024). "It has been reported that WNK1 affects the EMT of lung cancer cells through SNAI1 and enhances the mobility of lung cancer cells, which promoted us to examine the axis of ZYX/WNK1/SNAI1 in GC cells." (PMID 37692528, 2024). "In this study, we identified decreased expression of WASL and elevated expression of STK10 and WNK1 in the urine exosome of lung cancer patients by detection." (PMID 37980468, 2023). "In lung cancer cells and mouse tumor models, inhibiting the expression of WNK1 can reduce the expression of N-cadherin and smooth muscle actin induced by secreted protein acidic and rich in cysteine (SPARC)." (PMID 37652923, 2023). "ELISA and western blotting were used to investigate the expression changes of WASL, STK10 and WNK1 in the urine exosome of lung cancer patients." (PMID 37980468, 2023). "The secreted protein acidic and rich in cysteine (SPARC) secreted by extracellular matrix components can activate the expression of the WNK1 protein to promote the migration and invasion of lung cancer cells." (PMID 35313857, 2022). "Lymphocyte migration regulation related proteins were differentially expressed in the urine exosome of lung cancer patients, and WASL, STK10 and WNK1 may serve as potential biomarkers for lung cancer diagnosis." (PMID 37980468, 2023). "Some studies have found that the activation of Akt triggers WNK1-mediated lung cancer progression." (PMID 37652923, 2023). "Urine exosome WASL, STK10, and WNK1 were diagnosed with lung cancer, with a combined AUC of 0.760." (PMID 37980468, 2023). "Low expression of WASL and high expression of STK10 and WNK1 represent increased lymphocyte migration, which may be closely related to lung cancer development and progression." (PMID 37980468, 2023). "This is consistent with the low expression of WASL and high expression of WNK1 protein in lung cancer patients, which may explain why the age of 60–79 years is the peak of lung cancer incidence." (PMID 37980468, 2023). "But at present, the protein concentration changes of WASL, STK10 and WNK1 in the urine exosome of lung cancer patients are only preliminarily explored, and their relevance to the process of cancer cell metastasis is yet to be explored, requiring more in-depth exploration." (PMID 37980468, 2023). "This study is the first to report the expression of WASL, STK10 and WNK1 in the urine exosome of lung cancer patients, which may serve as potential biomarkers for lung cancer diagnosis." (PMID 37980468, 2023). "We then investigated the expression of WASL, STK10 and WNK1 in lung cancer patients." (PMID 37980468, 2023). "Changes in expression of WASL, STK10 and WNK1 may serve as potential biomarkers for lung cancer diagnosis and are of great importance for the selection of therapeutic targets in lung cancer." (PMID 37980468, 2023). "KLHL3 can degrade the expression of the WNK1 protein through ubiquitination, so it may have an important role in the progression of lung cancer." (PMID 35313857, 2022). "Our previous study found that activation of Akt triggers WNK1-mediated lung cancer progression." (PMID 28969021, 2017). "Studies have shown that most of the age of onset of lung cancer is over the age of 40, and the peak incidence is mainly concentrated in the age range 60–79, which is similar to the changes of WASL and WNK1 proteins in our experimental results." (PMID 37980468, 2023). "Lung cancer patients had reduced expression of WASL and increased expression of STK10 and WNK1 proteins in urine exosomes compared to normal people." (PMID 37980468, 2023).
lung carcinoma (continued). "The expression of STK10 and WNK1 was increased and the expression of WASL was decreased in the urine exosome of lung cancer patients compared with normal controls, with statistically significant differences (P < 0.05)." (PMID 37980468, 2023). "This study revealed that SPARC activated with no lysine (K) kinase 1 (WNK1) and its signaling pathways in lung cancer cells, and in a murine tumor model." (PMID 28969021, 2017). "Mechanistically, condition medium of CAF or exogenous kynurenine stimulated AKT, with no lysine 1 (WNK1) and cAMP response element-bindingprotein (CREB) phosphorylation in lung cancer cells." (PMID 27050278, 2016).
hereditary sensory and autonomic neuropathy type 2 (10 papers, 2012 to 2023). Hereditary sensory and autonomic neuropathy, type 2 (HSAN2) is an inherited disorder characterized by profound and universal sensory loss involving large and small fiber nerves, and marked hypotonia. "In humans, mutations in the HSN2 exon of WNK1 have been linked to Hereditary Sensory and Autonomic Neuropathy type II (HSANII), characterized by early onset neuropathy and a reduction of myelinated nerve fibers, amongst other defects." (PMID 37819975, 2023). "WNK1 and WNK4 have been identified as causative genes of pseudohypoaldosteronism type II (PHAII), and WNK1 is also a causative gene of hereditary sensory and autonomic neuropathy type 2A (HSAN2A)." (PMID 29494638, 2018). "WNK1 mutations have been identified as the cause of hereditary sensory and autonomic neuropathy type II, an early-onset autosomal disease of peripheral sensory nerves." (PMID 23285140, 2012). "In addition, our group recently reported mutations in a WNK1 isoform deemed to contain a nervous system–specific exon (formally referred to as the HSN2 gene in hereditary sensory and autonomic neuropathy type II (HSANII; OMIM #201300) disorder." (PMID 23451271, 2013). "WNK1 is also involved in the autosomal recessive neuropathy, hereditary sensory and autonomic neuropathy type II (HSANII)." (PMID 36151370, 2022). "Finally, mutations in exon HSN2 of WNK1, located within intron 8, are responsible for a form of congenital insensitivity to pain, HSAN2 (Hereditary Sensory and Autonomic Neuropathy type 2)." (PMID 22701532, 2012).
hepatoma (9 papers, 2020 to 2025). "In their study, overexpression of PPP2R1A counteracted the cell migration induced by increased WNK1 levels in HepG2 hepatoma cells." (PMID 39850502, 2025). "They suggested that PPP2R1A acted as a downstream effector in hepatoma, mitigating the enhanced cell migration driven by WNK1, a key protein kinase involved in tumor-induced angiogenesis." (PMID 39850502, 2025). "Elevated WNK1 mRNA and protein have been detected in hepatocellular carcinoma (HCC) and significantly correlated with poor prognosis, highlighting the clinical significance of WNK1 in HCC progression." (PMID 35813203, 2022). "To further address the role of PPP2R1A in WNK1 in hepatoma cell migration, we transfected HepG2 cells with WNK1 and PPP2R1A, and co-cultured them with the HUVEC cells for a transwell migration assay." (PMID 36292952, 2022). "Colony formation assays revealed that the overexpression of WNK1 promoted the proliferation of hepatoma cells, whereas silencing WNK1 inhibited the proliferation of hepatoma cells." (PMID 35368686, 2022). "Knockdown and inhibition of WNK1 also decreased tumor-induced ectopic vessel formation and inhibited tumor proliferation in two zebrafish models transplanted with intestinal and hepatocellular carcinomas." (PMID 35813203, 2022). "Overexpression of PPP2R1A can rescue the increased cell migration caused by WNK1 overexpression in HepG2, indicating that PPP2R1A is a downstream effector in hepatoma." (PMID 36292952, 2022). "In zebrafish experiments, genetic and chemical wnk1 knockdowns suppressed hepatoma tumor xenograft angiogenesis and tumor growth." (PMID 35326412, 2022). "The same tendency was observed in cellular invasion ability, WNK1 had a stimulative effect on the invasion of hepatoma cells." (PMID 35368686, 2022). "Analogously, the overexpression of WNK1 enhanced migration of hepatoma cells, whereas blocking WNK1 expression suppressed the migration of hepatoma cells." (PMID 35368686, 2022). "WNK1 was significantly overexpressed in hepatoma cells (HepG2 and HuH-7) compared to normal liver epithelial cells (THLE-3)." (PMID 35368686, 2022). "The results suggest that PPP2R1A acts as a repressor of WNK1 in stimulating the migration of hepatoma cells." (PMID 36292952, 2022). "Knockdown of WNK1 in endothelial cells diminishes hepatoma cell migration, and it can be rescued by OSR1 overexpression." (PMID 36292952, 2022). "The biofunctions of WNK1 in hepatocellular cancer (HC) cells were confirmed through qPCR, colony formation, and Transwell assays." (PMID 35368686, 2022). "Overexpressing WNK1 in HepG2 cells significantly enhanced the migrated cells, indicating that WNK1 is noteworthy in hepatoma cells for stimulating hepatoma cell migration." (PMID 36292952, 2022). "Subsequently, we detected the expression of WNK1 and its downstream effectors in hepatoma cells using human-specific primers." (PMID 36292952, 2022). "We further examined the efficacy of inhibition of WNK1 pathway in hepatocellular carcinoma (HCC) using an adult transgenic fish that overexpresses src tyrosine kinase in the liver driven by the hepatitis B protein x (HBx)." (PMID 32131390, 2020). "To understand the basis of the difference, we uncovered that xenotransplanted hepatoma cells produced WNK1." (PMID 32131390, 2020). "Our data suggest that WNK1 in endothelial cells enhances hepatoma cell proliferation and migration." (PMID 36292952, 2022). "Through further experiments in vitro, we have demonstrated that the overexpression of WNK1 could promote the proliferative, migratory, and invasive abilities of hepatoma cells, which unveiled its potent anticancer potential." (PMID 35368686, 2022). "Furthermore, using HUVEC endothelial cells co-cultured with HepG2 hepatoma cells, we confirmed that WNK1 plays a critical role in the induction of hepatoma cell migration in both endothelial cells and hepatoma cells." (PMID 36292952, 2022).
hepatoma (continued). "We also compared the migration behavior of Hep3B cells in WNK1 overexpression or knockdown in endothelial cells, and the results showed WNK1 overexpression in endothelial cells promoting hepatoma cell migration, while WNK1 knockdown in endothelial cells reduced the hepatoma cell migration." (PMID 36292952, 2022). "For example, high expression of WNK1 can predict poor overall survival (OS) in patients with hepatocellular carcinoma (HCC) and colorectal cancer (CRC), and is correlated with clinicopathological parameters such as high pathological grade and advanced clinical stage." (PMID 36123332, 2022). "Additionally, it was shown that overexpression of WNK1 in hepatocellular carcinoma enhanced the expression of MMP-2 and MMP-9, which are EMT-related proteolytic enzymes that can promote degradation of the extracellular matrix, EMT, and invasion." (PMID 35813203, 2022). "To further understand which downstream targets of WNK1 play critical roles during tumor-induced angiogenesis, we performed xenotransplantation and measured the expression of genes in endothelial cells and hepatoma cells." (PMID 36292952, 2022). "Moreover, overexpression of PPP2R1A can eliminate the increased migration ability induced by WNK1 overexpression in hepatoma cells, supporting the tumor suppressor role of PPP2R1A." (PMID 36292952, 2022). "Moreover, overexpression of OSR1 can rescue the reduced cell migration caused by shWNK1 knockdown in HUVEC cells, indicating OSR1 is downstream of WNK1 in endothelial cells promoting hepatoma cell migration." (PMID 36292952, 2022). "In addition, OSR1 overexpression in HUVEC cells can rescue the reduction of migrated cells caused by shWNK1, indicating that OSR1 is a downstream effector of endothelial WNK1 promoting hepatoma cell migration." (PMID 36292952, 2022). "Inhibition of WNK1 or its downstream kinases OSR1 (oxidative stress responsive kinase 1)/SPAK (Ste20-related proline alanine rich kinase) using chemical inhibitors decreased ectopic vessel formation as well as proliferation of xenotransplanted hepatoma cells." (PMID 32131390, 2020). "The expression of wnk1a and osr1b is upregulated in endothelial cells, and WNK1 and OSR1 are upregulated in hepatoma cells during tumor-induced angiogenesis." (PMID 36292952, 2022). "From the viewpoint of tumor xenograft angiogenesis, human hepatoma xenograft angiogenesis upregulates human VEGF and WNK1 and zebrafish wnk1." (PMID 35326412, 2022). "Knockdown of WNK1 in HUVEC cells with two independent shRNAs targeting on WNK1 (shWNK1-1 and shWNK1-2) significantly decreased the migrated hepatoma cells, WNK1 overexpression in HUVEC cells significantly increased the HepG2 migration." (PMID 36292952, 2022). "For the mechanistic study of the WNK1 axis in endothelial cells and cancer cells, we co-cultured the human umbilical vein endothelial cells (HUVEC) with HepG2 hepatoma cells and performed a transwell migration assay." (PMID 36292952, 2022). "Here, we show that human hepatoma cells xenotransplanted into zebrafish produced high levels of vascular endothelial growth factor (VEGF) and WNK1, and induced expression of zebrafish wnk1." (PMID 32131390, 2020). "Because WNK1 activates OSR1/SPAK, if OSR1 or STK39 are involved in tumor-induced angiogenesis, they are supposed to be upregulated from 2 dpi to 3 dpi, so these results indicate that WNK1 and OSR1 in hepatoma cells are involved in tumor-induced angiogenesis." (PMID 36292952, 2022).
glioblastoma (6 papers, 2018 to 2023). The most malignant astrocytic tumor (WHO grade IV). "In glioblastoma, WNK1 was involved both in resistance to TMZ-induced apoptosis and cell migration by controlling the NKCC1 cotransporter, but none of these studies focused on cancer cells with stem-like properties." (PMID 29930759, 2018). "WNK1 has been suggested as a substrate of AKT, with a potential role in regulating EMT and migration of glioblastoma and non-small cell lung cancer cells." (PMID 31898540, 2020). "WNK1 and 3 and their regulation of OSR1/SPAK and NKCC1 are essential for glioblastoma cell migration." (PMID 33604334, 2020). "Altogether these data establish a link between proteins of the Akt/SGK1/WNK1 signaling module and DDPM cytotoxicity both in quiescent TG1 and TG1-C1 GSC isolated from glioblastoma patients." (PMID 29930759, 2018). "WNK1 expression has been reported in patients’ glioblastoma and shown to modulate the activity of ion cotransporters of the NKCC family in primary glioblastoma cell lines leading to improved cell volume regulation and enhanced cell resistance to TMZ and cell motility." (PMID 29930759, 2018).
Hypokalemia (6 papers, 2022 to 2025). An abnormally decreased potassium concentration in the blood. "During hypokalemia, the kidney-specific WNK1 isoform (KS-WNK1) scaffolds the DCT-expressed WNK signaling pathway within biomolecular condensates of unknown function termed WNK bodies." (PMID 40493421, 2025). "Labeling of SPAK, a kinase downstream of lysine-deficient protein kinase 1 (WNK1) and WNK4 and upstream of NCC, demonstrated increased intensity and abundance of punctuated condensates resembling hypokalemia-related WNK+ bodies in the index patient compared with control samples." (PMID 39405114, 2024).